CD4 (CD4 molecule)
Diseases named in the same sentence as CD4 in open-access papers (continued):
Sharing a sentence is not in itself a finding about the gene and the disease.
psoriasis (continued). "In psoriasis, circulating CCR4 + CD4+ T cells significantly correlate with disease severity (PASI), and a strong negative correlation has been found for CCR5+ CD4+ T cells." (PMID 31963581, 2020). "In active psoriasis, we observe increased expression of IL17A, IL22 and IFN-γ in the effector T CD4+ and CD8+ cells of the epidermis in the immediate vicinity of keratinocytes, whereas cutaneous T cells show less activity of these genes." (PMID 31963581, 2020). "The absolute numbers and percentages of CD4+PD-1+ and CD8+PD-1+ T cells were significantly decreased in psoriasis patients when compared to controls." (PMID 32382290, 2020). "Recently, our group showed the effect of SK2 inhibition in a psoriasis mouse model using the modestly potent SK2 inhibitor, ABC294640, which diminished Th17 differentiation of naïve CD4+ T cells with concomitant reduction in SOCS1 mRNA levels." (PMID 33171607, 2020). "In contrast, topical Cal was reported to induce CD4+ Tregs in the dLNs32, and we found that Cal and Cal/BDP significantly suppressed the IL-23a expression in psoriasis-like skin lesions." (PMID 31705000, 2019). "In plaques of psoriasis patients, the frequency of FOXP3+ CD4+ T cells is increased when compared to healthy skins where only few Tregs are found in the dermis and epidermis." (PMID 30915067, 2019). "It was recently reported that Cal-BDP combination therapy increases CD4+CD25+Foxp3+CD127lo Tregs and reduces Th17 cells in the blood and skin lesions of patients with psoriasis, suggesting that Cal-BDP combination therapy restores the Treg-T17 balance." (PMID 31705000, 2019). "The production of IL-12 by CD4+ Th1 and CD8+ cytotoxic T cells along with IFN-γ and TNF-α in a pattern known as the type I cytokine pattern contributes to pathogenesis of psoriasis." (PMID 31130981, 2019). "As IL-21 expression was markedly increased in psoriasis patients and could promote CD4+ T cell proliferation and Th17 cell differentiation and also inhibited the expression of Foxp3, we then measured the proportion of Th17 and Treg cells in the PBMCs of psoriasis patients." (PMID 31440249, 2019). "In psoriasis, IL-22 is found to be produced by dermal CD4+ but also by epidermal CD8+ TC17 and CD4+ TH22 cells, as well as Innate Lymphoid Cells, and mast cells." (PMID 30555460, 2018). "The estimated odds of psoriasis decreased by 3.3% if the number of CD8+PD-1+ increased by 1 cell/μL, by 36.9% if percentages of CD4+PD-1+ cells increased by 1%, and by 29.5% if percentages of CD8+PD-1+ cells increased by 1%, on average." (PMID 29180838, 2017). "The absolute number of CD4+PD-1+ T cells correlated negatively only with PASI, and the absolute number of CD8+PD-1+ T cells correlated negatively only with the age of psoriasis onset." (PMID 29180838, 2017). "Functional analysis highlighted the roles of interferon signalling and the NFκB cascade, and we showed that the psoriasis signals are enriched in regulatory elements from different T cells (CD8+ T-cells and CD4+ T-cells including TH0, TH1 and TH17)." (PMID 28537254, 2017). "It is well known that the peripheral blood T cells, including CD4+ and CD8+ T cells, are involved in psoriasis following a persistent stimulation by immunogens." (PMID 29180838, 2017). "The result of the 100μg immunization dose is consistent with the reported reactivity to LL-37 by both CD4+ T cells and CD8+ T cells from psoriasis patients." (PMID 29091929, 2017). "Our results demonstrated that PSORI-CM02 upregulated the frequency of CD4+ Foxp3+ Tregs in vivo and promoted in vitro proliferation of CD4+ CD25+ Tregs as well, indicating that these Tregs play a role in attenuation of murine psoriasis by PSORI-CM02." (PMID 29358932, 2017). "Several researchers found decreased CD4+CD25+FOXP3+ T circulating cells both numerically and functionally in psoriasis patients." (PMID 28042206, 2016).
psoriasis (continued). "For example, KCs can drive skin auto-reactivity via Ag presentation to CD4+ and CD8+ T cells in animal models of psoriasis and toxic epidermal necrolysis." (PMID 27741278, 2016). "Success of alefacept in clinical trials of psoriasis and an excellent safety profile, provides a rationale to repurpose alefacept to reduce the HIV reservoir by depleting CD2hi CD4+ T cells." (PMID 27110598, 2015). "In this study, we found higher CD57 expression on CD4+ and CD8+ T cells in unaffected skin of psoriasis patients compared to lesional skin." (PMID 23468834, 2013). "We observed that the frequency of CD57+CD4+ and CD57+CD8+ T cells was significantly higher in unaffected skin of psoriasis patients compared to lesional skin." (PMID 23468834, 2013). "To do this, we assessed the extent of epigenetic and transcriptomic differences in CD4+ and CD8+ cells isolated from MZ twins discordant for psoriasis." (PMID 22291603, 2012). "A lymphocytic infiltrate in psoriasis plaques consists of a mixture of activated CD4+ and CD8+ T cells; the latter predominate in lesional epidermis and CD4+ cells in the dermis." (PMID 19830133, 2009). "Analysis of all samples, including both psoriasis patients and healthy controls, revealed significantly higher EZH2 expression in memory CD4+ or CD8+ T cells compared to their naïve counterparts, suggesting a potential role of EZH2 in T cell differentiation, independent of disease status." (PMID 41518566, 2026). "Our aim was to establish a human experimental model incorporating different CD4+ and CD8+ T cell subsets into a human full-thickness skin equivalent (hFTSE) to investigate their individual and combined contribution to the pathogenesis of psoriasis." (PMID 42039187, 2026). "Emerging evidence suggests that skin-primed memory CD4+ and CD8+ T cells, amplified and activated within psoriatic lesions, may circulate contributing to the systemic inflammation observed in psoriasis patients." (PMID 40599782, 2025). "The IL-23–Th17 cell axis is central to psoriasis inflammation development, where IL-23 promotes the differentiation of T cells into IL-17-producing CD4+ T helper cells (Th17), CD8+ cytotoxic T cells (Tc17), and IL-22-producing CD4+ T helper cells (Th22)." (PMID 41376622, 2025). "AD and psoriasis are believed to be pathologic cutaneous manifestations of 2 separate CD4+ lineages which typically do not coexist." (PMID 40535962, 2025). "A recent study using NF-κB−/− mice showed that IL-17 A-producing Vγ4-/Vδ4-positive γδ T cells, but not CD4-positive traditional Th17, are major cellular sources of IL-17 A associated with the pathophysiology of IMQ-induced psoriasis." (PMID 40481552, 2025). "For instance, in systemic sclerosis and psoriasis, dysregulated genes like CCL2 and CCR7 contribute to fibroblast activation and the infiltration of CD4+ T and NK cells through IL-17 signaling pathway, PPAR signaling pathway, leading to skin involvement and arthritis." (PMID 40534874, 2025). "In the CD4+ T cell compartment, the percentage of TEM was markedly increased in mice with recurrent psoriasis-like inflammation; whereas in the CD8+ T cell compartment, TCM cells showed a more pronounced expansion, suggesting an accumulation of long-term memory T cells in the inflammatory setting." (PMID 40599782, 2025). "CD4+ and CD8+ T cells producing IL-17 have been identified in psoriasis lesions." (PMID 40995368, 2025). "Given the important role of immune cells in psoriasis, we hypothesized that AGAP2-AS1 in HaCaTs could be taken up by CD4+ T cells via exosomes, thus promoting the differentiation of Th1 and Th17 cells." (PMID 40520230, 2025). "Here, we aimed to investigate (i) the establishment of CD4+ and CD8+ T cell memory, (ii) the accumulation of activated and terminally differentiated T cells, and (iii) the potential link with vascular inflammation, in a mouse model of recurrent psoriasis." (PMID 40599782, 2025).
psoriasis (continued). "Building on this finding, by modeling the internal environment of psoriasis, we hypothesize that TNF-α-treated HaCaTs-derived exosomes can deliver AGAP2-AS1 to CD4+ T cells, potentially promoting CD4+ T cell differentiation towards Th1 and Th17 phenotypes." (PMID 40520230, 2025). "In the IMQ-induced psoriasis mouse model, this approach reduced epidermal thickness, inhibited infiltration of CD3+ T cells and CD4+ T cells, lowered serum IL-17A and IFN-γ levels, and normalized spleen indices, demonstrating systemic anti-inflammatory effects." (PMID 41226338, 2025). "In psoriasis, the CD4/CD8 ratio of 2.1:1 is also on the side of the CD4-positive cells." (PMID 40981339, 2025). "Notably, while in healthy skin IL-17A is produced mainly by CD4+ T cells and IFN-γ is produced predominantly by CD8+ T cells, in psoriasis, both CD4+ T cells and CD8+ T cells co-produce both IL-17A and IFN-γ." (PMID 38642273, 2024). "In addition, multiple studies have underscored the significant contributions of Th1, Th17, Tfh, CD4+ TRM, and CD4+ γδT cells, along with their secreted cytokines, in the development of psoriasis 47-51." (PMID 38617532, 2024). "Moreover, IL-1R1 blockade significantly reduced the population of IL-17 A-producing γδ T cells, CD4+ T cells, and CD8+ T cells, consistent with the role of IL-1β in the development of IL-17 A-producing T cells and psoriasis pathogenesis." (PMID 38704587, 2024). "Although inflammatory cell infiltrates (CD4+ and CD8+ T lymphocytes) are observed in both AA and vitiligo lesions, those inflammatory cells are less densely populated than in other inflammatory skin diseases, like atopic dermatitis and psoriasis." (PMID 38673994, 2024). "To further assess the role of Ca2+ influx-induced [Ca2+]ex drop in psoriasis pathology, we established psoriasis model by applying IMQ cream to the ear using R26-LSL-CEPIAexternal;Itgal-LSL-Clover;Itgb2-LSL-mRuby2;CD4-Cre mice and injected with SKF96365 or DMSO daily for 7 days." (PMID 39033133, 2024). "In addition to the use of cytokines, HSEs with integrated CD4+ T cells or TH1- and TH17-polarized T cells have already been developed to study the pathogenesis of psoriasis." (PMID 38251799, 2024). "We previously reviewed 13 studies on the treatment of psoriasis with fire acupuncture plus TCM in 1088 cases and compared the total effective rate, PASI score, DLQI score, extent of lesion area, presence of pruritus, CD4+/CD8+ ratio, and relapse rate." (PMID 38363920, 2024). "In addition to infectious diseases, CD4+ and CD8+ TRM cells have been observed in various pathological conditions, including psoriasis, allergic asthma, inflammatory bowel disease (IBD), and other inflammation-related diseases in mice and humans." (PMID 39193473, 2024). "Still, single-cell analysis of skin tissues and peripheral blood mononuclear cells from Palmoplantar pustulosis, a specific psoriasis subtype, revealed heightened expression and co-expression of TH17 (KLRB1/CD161) and TH2 (GATA3) in a subset of memory CD4+ T cells." (PMID 38596682, 2024). "Similarly, S12 and S14 reduce the infiltration of CD4+, CD8+, and CD11c+ cells in mouse models of psoriasis." (PMID 38067173, 2023). "Intriguingly, the proinflammatory cytokine IL-23 has been identified as a stimulant for CDK7 expression in CD4+ T cells, further amplifying glycolytic activity through activation of the PKB/mTOR/HIF-1α signaling network in a psoriasis-like mouse model induced by imiquimod (IMQ)." (PMID 38035065, 2023). "Regarding CD4 T cells, a positive correlation with serum CRP was observed only with the percentage of CCR6+ terminally differentiated effector memory cells re-expressing CD45RA (EMRA) in patients with psoriasis." (PMID 37958689, 2023).
psoriasis (continued). "Another study found that TNFi therapy in psoriasis and IBD patients led to increased peripheral IFN-γ, IL-17, IL-10 and the proliferative response of CD4+ T-cells to T-cell receptor stimulation, while biopsied target tissues showed decreased Th1/Th17 cytokines and inflammatory genes." (PMID 37681925, 2023). "Similarly, in the psoriasis (PS) dataset, our analysis revealed the presence of ten clusters encompassing CD8+ T cells, CD4+ T cells, NK cells, and dendritic cells." (PMID 37700026, 2023). "In addition, 84.7% of CD161+ T-cell cluster cells expressed CXCL13, while only 1.6% of CD8+ T-cell cluster cells, 2.5% of CD4+ T-cell cluster cells, and 0.6% of Treg cluster cells expressed CXCL13 in pretreatment psoriasis lesional skin." (PMID 37781383, 2023). "Regarding PASI, BSA and the duration of psoriasis, we found a positive correlation between the expression of CD4/CD69 within CD4 and PASI: the more severe the psoriasis was, as assessed via PASI, the higher percentages of CD4/CD69 within CD4+ lymphocytes." (PMID 37892710, 2023). "Because the differentiation of naïve CD4+ helper T cells into Th17 cells is the fundamental process of psoriasis development and requires glycolysis as an energy source, it is possible that CD147 participates in the pathogenesis of psoriasis." (PMID 38139173, 2023). "Studies have shown that CXCL16 has chemotactic effects on CD4+ T cells, and further activates CD8+ T cells, thereby promoting the secretion of IFN-γ, IL-17 and TNF-α, etc., and is involved in the pathogenesis of psoriasis progress." (PMID 35693833, 2022). "Compared with psoriasis without arthritis, T cells CD4 memory activated were increased in psoriasis with osteoarticular involvement, while T cells CD4 memory resting were decreased." (PMID 35371093, 2022). "IL-17 therapeutic blockade decreased CD3+CD4+CCR6+, CD3+CD4+CXCR3+, CD3+CD4+CCR6-CXCR3+(Th1), CD3+CD4+CCR6+CCR4+(Th17), CD3+CD4+CCR6+CCR4+CXCR3+(CXCR3+-Th17), and CD3+CD4+CCR6+CCR4-CXCR3+(Th17.1) cell populations in responding psoriasis patients." (PMID 35925616, 2022). "Several immunological studies demonstrated that patients with psoriasis had abundant memory T lymphocytes that did not undergo natural apoptosis, including CD4+ and CD8+ T lymphocytes." (PMID 35629363, 2022). "Administration of ndSTAT1-TMD to psoriasis- and IBD-induced mice effectively attenuated the clinical symptoms of diseases and delayed disease progression by restoring the disrupted imbalance of CD4+ effector T cells in the secondary lymph organs." (PMID 36591260, 2022). "Interestingly, the pathogenesis of psoriasis lies upon dysregulation and overexpression of helper T-cells including CD3+ and CD4+ T-cells." (PMID 35987944, 2022). "The CD4/CD8 ratio is an important marker to differentiate acute and chronic lesions of psoriasis." (PMID 33936220, 2021). "In psoriasis, CD4+, CD8+ as well as CD4–CD8– (double negative) T cells are involved in the molecular pathogenesis following their stimulation by (auto-)antigens." (PMID 34746142, 2021). "In our study, we found that the number of CD4+ CD25+ FoxP3+ Treg cells was also not altered in psoriasis patients, but we did not conduct in-depth research on Treg cells." (PMID 35186952, 2021). "In psoriasis, IL-17+ IFN-γ+ CD4+ lymphocytes as well as high levels of IL-17, IFN-γ, and TNFα in the blood could suggest the presence of pathogenic Th17 cells and the existence of a systemic component." (PMID 32801996, 2020). "In contrast, we demonstrated that MTX, one of the effective traditional drugs for the treatment of psoriasis, lowered the frequency of CD4+, but not CD8+, TCM cells." (PMID 32929360, 2020). "In the IMQ induced psoriasis-like mice, (R)-Salbutamol administration reduced the expression of IL-17 in plasma along with a downregulation of the CD4+ Th17+ T cells (Th17) and upregulation of the CD3+CD4+ T cells and CD25+ Foxp3+ Tregs in the spleens." (PMID 32102363, 2020).
psoriasis (continued). "IL-17A is not only secreted by CD4+ Th17 cells, but also by CD8+ T cells and certain cells of the innate immune system including neutrophilic granulocytes, thus further highlighting the tight connection of innate and adaptive immunity in psoriasis." (PMID 31402919, 2019). "Recently, N-3 PUFAs have been reported to increase the number of CD4+CD25+Foxp3+Treg cells and to decrease Th17 cell differentiation and IL-17 production in other disease models including encephalomyelitis and psoriasis." (PMID 29543869, 2018). "Th17 cells are derived from CD4+T cells in the presence of IL-6, IL-23, and TGF-β, which play a central role inthe chronic inflammatory diseases (psoriasis in particular) and are consideredresponsible for the chronic course of psoriasis." (PMID 29630472, 2018). "CD4+ T cell recognition of Malassezia antigens resulting in a Th1 response has been reported in psoriasis, though it has not been studied in spondyloarthritis." (PMID 29675414, 2018). "This response appears to be restricted to CLA+CD4+ memory T cells since CD4-depleted CLA+ memory T cells do not respond to this microorganism in a coculture model with psoriasis cells." (PMID 30013558, 2018). "Draining lymph node and spleen cells were isolated from IMQ-induced psoriasis-like mice 7 days after treatment without or with esculetin, and CD4+Foxp3+ Tregs were detected via flow cytometric analysis." (PMID 30258447, 2018). "Finally, almost all patients with PsA have psoriasis and we have shown that LL37 is a CD4 and CD8 T cell autoantigen in at least 46% of psoriasis patients." (PMID 30279686, 2018). "Interestingly, depleting CD4+Foxp3+ Tregs largely reversed esculetin-mediated reduction in PASI scores, indicating that esculetin attenuates murine psoriasis mainly by inducing CD4+Foxp3+ Tregs." (PMID 30258447, 2018). "In this study, we use RNA-seq to assess the transcriptomic differences between scalp, palmoplantar, and conventional psoriasis and use flow cytometry to profile the cytokines secreted by CD4+ T effector cells, CD8+ T effector cells, and CD4+ regulatory T cells (Tregs)." (PMID 30054515, 2018). "Therefore, we quantified CD4+ Foxp3+ Tregs in spleens and lymph nodes of psoriasis-like mice in vivo and determined the effects of PSORI-CM02 on CD4+ CD25+ Treg proliferation in vitro." (PMID 29358932, 2017). "Interleukin 16 (IL-16) has been described as a significant cytokine involved in the recruitment of CD4+ cells during inflammation; however, its potential role in psoriasis has not been defined." (PMID 27788245, 2016). "In this study, suppression of NRIP1 in CD4+ T cells also decreased the secretion of IL-17 significantly, suggesting that NRIP1 may involve in psoriasis via upregulating IL-17." (PMID 27708240, 2016). "A similar pattern of CD4+ T-cell activation through antigen presenting dendritic cells stimulate the proliferation of CD8+ T-cells, with activity of the T-helper 1 phenotype inflammation that prevails in both psoriasis and atherosclerosis." (PMID 27448600, 2016). "Whether CD57+CD4+ and CD57+CD8+ T cells can contribute to psoriasis immunopathogenesis remains poorly understood." (PMID 23468834, 2013). "Additionally, some genes may show altered expression in bulk samples of psoriasis lesions because of shifts in cellular composition; for instance, lesions contain more CD4+ T-cells than normal skin and may thus show increased expression of genes expressed specifically by CD4+ T-cells." (PMID 24260178, 2013). "We also assessed functionality of the T cells by evaluating the secretion of several inflammatory cytokines (IL-17A, IFN-gamma, IL-2, IL-33, TNF-alpha, IL-21, IL-22, and IL-27), from cell-sorted purified CD4+ and CD8+ T cells isolated from lesional and unaffected skin biopsies of psoriasis patients." (PMID 23468834, 2013).